CCR2 (C-C motif chemokine receptor 2)
Diseases named in the same sentence as CCR2 in open-access papers (continued):
Sharing a sentence is not in itself a finding about the gene and the disease.
infection (continued). "In the current study, we demonstrate that inflammatory monocyte infiltration into the brain during acute TMEV infection requires CCR2 and that neurons are a key source of CCL2 driving this trafficking during the earliest stages of infection." (PMID 29202854, 2017). "CCL2, also known as monocyte chemoattractant protein-1, is involved in chemotaxis of CCR2-expressing memory T cells, monocytes, and DCs to sites of inflammation produced by either tissue injury or infection." (PMID 28261205, 2017). "The receptors that bind the main chemokine attractants of monocytes (CCR1 for CCL3 and CCR2 for CCL2) that mediate monocyte recruitment to sites of infection were equally expressed on the monocytes of the three groups." (PMID 29116124, 2017). "A temporal analysis revealed that they were the first responders to infection and arrived independently of Ccr2 signaling." (PMID 28844797, 2017). "85% of Ly6Chi monocytes co-expressed CCR2 and F4/80 at d14 and 21p.i.; the frequency then decreased to 50% at later time points of infection." (PMID 28892492, 2017). "We were able to define CD11b+CD24lowCD64+Ly6C+CCR2+CX3CR1+ inflammatory monocytes as the preferred mononuclear host cell for L. major following the initial neutrophil phase of infection." (PMID 28666021, 2017). "Natural killer cells are capable of migrating to virus-infected tissue and specifically for IV infection, CCR2 was shown in mice to mediate the migration of NK cells during influenza virus infection." (PMID 28261217, 2017). "Strikingly, Ccr2-/- mice also produced significantly less IFNγ at both 24 and 48 hours post-infection when compared to WT mice, in agreement with recent findings." (PMID 28384349, 2017). "Macrophage and dendritic cell precursors (MDP) in the bone marrow give rise to Ly6Chi monocytes or inflammatory monocytes, which exit the bone marrow in a CC-chemokine receptor 2 (CCR2)- dependent manner in response to infection to the inflamed tissues." (PMID 26973640, 2016). "Our results indicate that following intranasal infection with 1.2x106 plaque forming units of HSV-1, CCR2 deficiency in hematopoietic cells and, to a lesser extent, in CNS exacerbates the outcome of HSE." (PMID 27930721, 2016). "Ly6C+ monocytes in the bone marrow are mobilized in response to inflammatory stimuli and those coexpressing high levels of CC-chemokine receptor 2 (CCR2) traffic to sites of infection where CCR2 ligands are produced." (PMID 27382187, 2016). "At day 25 of infection, the frequency of virus infected DCs dropped dramatically, although CCR2+ DCs remained the major infected DC subset." (PMID 26808628, 2016). "Overall, these results indicate that CCR2 signaling in cells of the hematopoietic system is involved in the mobilization of both monocyte subsets into the blood following infection in our mouse model of HSE." (PMID 27930721, 2016). "The infiltration of blood leukocytes into the CNS of CCR2-/-, CCR2-/-→WT, WT→CCR2-/- and WT mice was evaluated by flow cytometry analyses prior to (day 0) and on days 4, 6, 8 and 10 following infection with HSV-1." (PMID 27930721, 2016). "Upon infection, myeloid-derived CCR2hi Ly6Chi monocytes, CCR2+ Ly6Cint, and CCR2+ Ly6Clow mononuclear cells were recruited to the brain of mice." (PMID 26984535, 2016). "Levels of blood leukocytes in CCR2-/-, CCR2-/-→WT, WT→CCR2-/- and WT mice were evaluated by flow cytometry analyses prior to (day 0) and on days 4, 6, 8 and 10 following infection with HSV-1." (PMID 27930721, 2016). "After 2 weeks of anti-CCR2 antibody administration (28 days after infection), Ly6Chi monocyte numbers were still significantly reduced in the blood." (PMID 26984535, 2016). "The distribution of HSV-1 antigens was evaluated by immunohistochemistry analyses in the brain of WT, CCR2-/-, CCR2-/-→WT and WT→CCR2-/- groups following intranasal infection." (PMID 27930721, 2016).
infection (continued). "Depletion of CCR2+ Mo before infection leads to decreased transport of fungal spores to the draining lymph nodes, which prevents A. fumigatus-specific CD4+ T cell priming." (PMID 26973640, 2016). "Administration of anti-CCR2 or anti-Gr-1 mAb during an ongoing PbTg infection also resulted in reduced IFNγ levels in the brains, which was significant in the case of anti-Gr-1, demonstrating again a strong effect of this clone." (PMID 25884830, 2015). "Recently, another chemokine receptor, Ccr2, has also been shown to mediate macrophage recruitment following hindbrain infection of M. marinum in zebrafish embryos." (PMID 25573892, 2015). "Monocytes require CCR2 to leave the bone marrow and therefore—to substantiate our findings—we compared the outcome of PbTg infection using anti-CCR2 mAb as well as anti-Gr1." (PMID 25884830, 2015). "From day 2 post-infection, a proportion of CCR2+ monocytes up-regulated CD11c and MHC II and down-regulated Ly6C, indicating that they differentiated to DCs." (PMID 26431538, 2015). "In bacterial infection, the CCR2-expressing CD11b+Ly6Chi cells (and their differentiation products) are generally required to control infection by direct killing of bacteria." (PMID 26468944, 2015). "Animals that received applications of the anti-CCR2 antibody on days 3 and 5 after infection, showed decreased amounts of lymphocytes and especially Ly6Chi monocytes." (PMID 25884830, 2015). "CCR2 was required for host protection during Y. pseudotuberculosis mE infection, and curiously, its function was more important in the adaptive response stage." (PMID 26468944, 2015). "CCR2-dependent monocytes-derived DCs rapidly accumulate in the oral mucosa during infection and directly present Candida-derived antigen in the draining lymph nodes." (PMID 26431538, 2015). "After infection, the de novo recruited CCR2+ monocytes give rise to CD11c+CD11b+F4/80+CD103− intestinal macrophages (MPs) within the lamina propria." (PMID 26269452, 2015). "When infection was carried out with the translocation-deficient strain ΔBmE, similar numbers of ET cells were present in C57BL/6 and Ccr2-/- mice, even though the two groups of mice were colonized to different levels by this strain." (PMID 26468944, 2015). "Here, we provide initial evidence that Ly6Chi inflammatory monocytes are essential immune players in PbTg infection since specific depletion by injection of anti-CCR2 mAb protected PbTg-infected mice from ECM pathology." (PMID 25884830, 2015). "Ly6C+ monocytes are recruited in CCR2 dependent manner and help initiate protective T cell responses following infection with Mycobacterium tuberculosis, Leishmania major, and Cryptococcus neoformans." (PMID 24945711, 2014). "Lung sections from CCR2 depleter mice showed extensive and progressive hyphal growth starting at day +3 post infection (p.i)." (PMID 24586155, 2014). "Strikingly, CCR2 depleter mice treated with DT uniformly succumbed to infection when challenged with inocula that ranged from 4–8×107 conidia." (PMID 24586155, 2014). "Our results points to CCL2/CCR2 signaling as a crucial element in the development of neuroinflammation in the first days following a peripheral infection." (PMID 25065370, 2014). "In aggregate, our studies find a novel essential function for CCR2+Mo in innate defense against a pulmonary fungal pathogen by mediating indirect and direct containment of fungal cells at the portal of infection." (PMID 24586155, 2014). "CD11b+Ly6chighLy6G− inflammatory monocytes are reported to contribute to T. brucei-induced pathogenicity development through their production of TNF, whereby in the acute phase of infection their emigration from the bone marrow is CCL2/CCR2-dependent." (PMID 25255103, 2014). "DT-treated CCR2 depleter and control mice showed similar kinetics and magnitude of neutrophil recruitment during the early phases of infection." (PMID 24586155, 2014).
infection (continued). "The similar increase of IFN-γ levels in Ccr2-null animals and controls after infection with P. chabaudi was reflected by an analogous upregulation of Sca-1 in BM Ccr2-null LIN− cells and the amalgamation of HSC and HPC compartments." (PMID 23762028, 2013). "CCL2 is primarily produced by monocytes and macrophages and recruits monocytes to sites of active infection, exerting its effect through its receptor CCR2." (PMID 23265239, 2013). "While CCR2 enables recruitment of inflammatory monocytes to sites of infection, the factors that coordinate their activation and acquisition of effector function are not known." (PMID 24130498, 2013). "We also established that in CCR2 deficient mice IFN-γ and CCL2 induction by infection with P. chabaudi was similar to infected wild type mice whereas CCL7 was constitutively deregulated." (PMID 23762028, 2013). "CCR2 is expressed by many inflammatory cells and allows for their recruitment to the lungs following infection by many respiratory pathogens." (PMID 23633954, 2013). "Ccr2-null mice exhibited a similar upregulation of IFN-γ plasma levels within the first four days after infection compared to controls demonstrating a virtually intact IFN-γ response of CCR2 deficient hosts." (PMID 23762028, 2013). "Studies using mouse models of infection, inflammation, and graft rejection have demonstrated that CCR2-deficient (CCR2−/−) mice exhibit enhanced Th2-type responses with increased production of IL-4 and IL-5, but decreased production of IFN-γ." (PMID 23472158, 2013). "For the first time in an infection model, we have shown that the majority of CCR2+ monocytes in the footpads of B6.WT mice also express CCR7." (PMID 24205367, 2013). "Similar to our L. major model, CCR7-/- mice infected with T. gondii show a reduced migration of CCR2+ inflammatory monocytes to the site of infection." (PMID 24205367, 2013). "Analysis of liver leukocytes from infected mice revealed a significant decrease in Ly6ChiLy6G−CD11b+ inflammatory monocytes in CCR2−/− mice five days post-infection compared with wild-type mice." (PMID 23300453, 2013). "Nevertheless, elevated levels of MCP-1 persisted throughout the yopK infection in vivo and the MCP-1 receptor, CCR2, was involved in host defense." (PMID 23633954, 2013). "Although Th1 effectors depend upon CXCR3 to reach the site of infection, inflammatory monocytes require chemokine receptor CCR2 for optimal trafficking." (PMID 24130498, 2013). "The percentage of CCR2+ or CCR5+ T cells during infection was increased in relation to naive mice; in vivo treatment with losartan or captopril abolished this effect." (PMID 23646169, 2013). "Our data show that CXCR3 enables Th1 recruitment to the intestinal LP, where these cells instruct activation of CCR2-dependent inflammatory monocytes, in turn controlling infection." (PMID 24130498, 2013). "Binding to its seven-transmembrane G-protein-coupled receptor CCR2 (CC chemokine receptor 2) results in signaling events that lead to the recruitment of monocytes in a variety of in vivo experimental models of infection and injury." (PMID 24312451, 2013). "In wild type hosts the infection-induced mobilization of myeloid progenitors via CCL2/CCR2 resulted in the presence of “CD27+ CMPs” and “GMPs” in the spleen, inversely corresponding to their loss from BM following infection." (PMID 23762028, 2013). "Taken together, in line with our study, these studies demonstrate that during inflammation, NK cells can be recruited in a CCR2-dependent manner to the site of infection." (PMID 23272202, 2012). "In the high dose infection, there was a significant decrease in both recruited neutrophils and recruited monocytes in the Gr-1+ cell-depleted CCR2 KO mice." (PMID 23284825, 2012). "Upon infection with influenza virus, the relative proportions of CCR2−/− (CD45.2) to wt (CD45.1) NK cells responding to infection in the spleen and lungs barely changed over the course of infection (day 3 and 5 p.i.))." (PMID 23272202, 2012).
infection (continued). "It has been shown previously that emigration of inflammatory monocytes from bone marrow into the circulation during infection with Listeria monocytogenes, an intracellular bacterial pathogen requires the chemokine receptor CCR2." (PMID 22452607, 2012). "The chemokine receptors involved in NK cell migration to the site of infection have been assessed for a few pathogens, and from these studies it appeared that CCR2, CCR5, CXCR3 and CX3CR1 play a key role in NK cells migration during infection." (PMID 23272202, 2012). "As also monocyte-precursors undergo vigorous proliferation in the bone marrow (BM) during infections and then egress CCR2-dependently, we decided to determine the role of CCR2 in NK cell migration during intranasal influenza virus infection." (PMID 23272202, 2012). "During Listeria infection, chemokine receptor-mediated signalling is required for egress from the BM only, as CCR2−/− or pertussin toxin-treated monocytes injected into the bloodstream of L. monocytogenes-injected mice readily migrate to the site of infection." (PMID 23272202, 2012). "On the individual gene level PRDX2, an antioxidant enzyme was enriched in the acute stage of secondary DENV infection, while at defervesence, CCR2 was among the transcripts seen upregulated in secondary infection." (PMID 21810247, 2011). "Upon infection of mice with Listeria monocytogenes or Leishmania major recruited inflammatory monocytes differentiate into Tip-DCs at sites of infection in a CCR2-dependent manner." (PMID 21124820, 2010). "To further support a role for Tip-DCs in pathogenicity during T. brucei infection, we transferred their CD11b+Ly6C+ monocytic cell precursors purified from the bone marrow of WT infected mice into infected recipient CCR2 KO mice on day 6 post infection." (PMID 20714353, 2010). "Gr1+CCR2+CX3CR1lo monocytes emigrate from the BM in response to infection and home to sites of inflammation, where they are able to differentiate into DCs." (PMID 20399121, 2010). "It is, therefore, not clear why there is still significant hemoconcentration in CCR2–/– mice at day 6 after infection, despite decreased cytokine levels, liver damage and lethality rates." (PMID 21206747, 2010). "Recent studies in L. monocytogenes and T. gondii model have shown that Ly-6Chigh inflammatory monocyte recruitment to sites of infection involved CCR2-mediated emigration of monocytes from the bone marrow into the bloodstream." (PMID 19557162, 2009). "Murine Gr-1+ CCR2+ monocytes (which correspond to the CD14high human blood monocytes used in the present study) are recruited to sites of infection where they differentiate into inflammatory DCs." (PMID 19229322, 2009). "Monocytes in CCR2−/− mice fail to exit the bone marrow efficiently during infection." (PMID 39714174, 2025). "Ccr2-/- mice exhibited exaggerated Th2 cell responses in the lung and spleen following infection." (PMID 39903705, 2025). "The elevated expression of CCR2 in lung tissue and various immune cell populations, including DCs, Mφ, and monocytes, underscores its potential role in facilitating the recruitment and activation of immune cells during infection." (PMID 39903705, 2025). "MLN Mtb burden was lower than at 4 weeks post-infection, as expected, but was not affected by CCR2 or CX3CR1 deficiency at the earlier time point." (PMID 40497732, 2025). "For example, although targeting the CCL2/CCR2 axis can reduce the infiltration of TAMs, it may inhibit the protective effect of macrophages in infection or tissue repair." (PMID 41445742, 2025). "Early infection triggered a monocyte-specific antiviral response marked by changes in the expression of genes associated with lipid metabolism (LIPA, lysosomal acid lipase) and chemotaxis (CCR1 and CCR2)." (PMID 41332545, 2025). "Immune cell recruitment following EV-D68 infection is impaired in Ccr2–/– mice." (PMID 40459936, 2025).
infection (continued). "However, the addition of CCR2 antagonists on day 28 partially restored the levels of TNF-α and IFN-γ caused by H37Ra infection, suggesting that immunosuppression was reversed." (PMID 41562082, 2025). "We used these different infection conditions to examine the importance of parasite antigens (via heat-killed parasites) or parasite replication (via UV-treated parasites) in driving the CCR2+ monocyte response to T. gondii in the brain." (PMID 40492741, 2025). "This hypothesis is supported by our data showing upregulated CCR2 expression on pulmonary dendritic cells, macrophages, and monocytes following infection, along with reduced immune cell infiltration observed in ccr2-/- mice." (PMID 39903705, 2025). "CCR2+ monocyte infiltration of the brain coincides with parasite entry to the brain during acute infection, and these cells persist in the brain during the chronic stage of infection." (PMID 38206985, 2024). "It is clear that CCR2 blockade in the chronic phase of infection is fatal." (PMID 38206985, 2024). "Interestingly, downregulated genes also carried roles seen in systemic inflammatory response and susceptibility to infection, including TNSF12, CCR1, and CCR2." (PMID 39666613, 2024). "The mechanism by which CCR2- TVM-derived TRM cells exert their effector function against infection, the tumor microenvironment, and inflammatory conditions remains unclear." (PMID 39193473, 2024). "Furthermore, we found that the removal of CCR2+ monocytes or CD11c+ innate cells significantly increased lung fungal burden at day 4 post-infection with Cn-H99." (PMID 39324785, 2024). "However, upon infection, the livers of Ccr2–/– mice had markedly less macrophages and drastically more neutrophils compared to the livers of WT mice." (PMID 39541153, 2024). "Meanwhile, IL-10 was not induced by infection, and no discernible difference in its expression levels was observed between WT and CCR2-deficient mice." (PMID 39051675, 2024). "Importantly, Ccr2–/– mice have intact tissue-resident macrophage populations but are unable to recruit additional monocytes in the event of infection." (PMID 39541153, 2024). "To investigate this, we first assessed ccl2 and ccr2 transcript abundance after infection." (PMID 38307625, 2024). "However, an intriguing study showed that CCR2 deficiency results in better clinical outcomes in mice upon JEV infection, while CCL2 deficiency renders mice highly susceptible to infection." (PMID 38997413, 2024). "Mice treated with α-CCR2 lost comparable weight to isotype controls on day 1 post infection." (PMID 39127259, 2024). "However, Ccr2/Ccr7 double knockouts eliminate iMO recruitment following infection with either virus, indicating these receptors together control iMO recruitment." (PMID 38658802, 2024). "Thus far our data suggest that CD11c+ cells, which include CCR2+ Mo-derived cells, are key for the activation of T cells in response to HK-fbp1 immunization via roles during initial priming and re-expansion after infection." (PMID 39324785, 2024). "We hypothesised that the increase in expression of Cxcl12/Ccl2/Ccr2 signalling axis components in miR-126 knockdown embryos is responsible for the recruitment of macrophages to infection." (PMID 38307625, 2024). "As expected, we found that CCL11 together with CCL2, CCL3, and the receptors CCR2, CCR3, and CCR5 were all upregulated in newly-weaned hamster brain tissues after Delta variant infection at 2, 4, and 7 dpi, of which CCL11 and CCR2 were significantly higher at 4 dpi." (PMID 37122119, 2023). "Knockout of CCL2 or its principal receptor, CCR2, slightly reduced macrophage infection in culture." (PMID 37085605, 2023). "Effects of Tlr4 KO and Ccr2 KO on leptomeningeal EC responses to infection." (PMID 37318981, 2023). "Due to the limited availability of CCR6ko mice, we tested CCR2ko mice in the current study because the role of CCR2 in MmuPV1 infection, especially in the oropharyngeal tissues, is unknown." (PMID 38133335, 2023).